AR (androgen receptor)
Diseases named in the same sentence as AR in open-access papers (continued):
Sharing a sentence is not in itself a finding about the gene and the disease.
prostate carcinoma (continued). "Throughout the development of prostate cancer, AR expression levels tend to gradually increase, particularly in CRPC, where the expression of AR protein significantly rises." (PMID 40008000, 2025). "We also investigate the maximum vital goals in prostate cancer therapy such as AR, prostate specific antigen (PSA), AKT, cyclin B1, cyclin dependent kinase (CDK1), phospho‐androgen receptor (p‐AR), and phospho‐CDK1 (p‐CDK1: T161) expression." (PMID 40336533, 2025). "To validate our MPS as a platform for reporting treatment responses in bone metastasis in prostate cancer, we initially created an MPS containing only spheroids of DU-145, LNCaP, and LAPC4 cell lines, which differ in AR status." (PMID 40596459, 2025). "In addition to the key roles of androgens and AR in the regulation of prostate cancer pathogenesis, a variety of hormone-responsive GPCRs are also involved in the occurrence and development of prostate cancer, so they may serve as potential alternative drug targets for prostate cancer intervention." (PMID 41347146, 2025). "The recent findings that AR antagonists promote the response to immune checkpoint inhibitors in castrate-resistant prostate cancer (CRPC) further support the role of AR in modulating the immune response." (PMID 39837817, 2025). "The BET proteins (BRD2/3/4) are key epigenetic co-regulators mainly for prostate cancer growth, with BRD4 being a critical component of AR signaling." (PMID 40407591, 2025). "In prostate cancer, for instance, FOXA1 functions as a cofactor for the androgen receptor (AR), co-localizing at enhancers to coordinate hormone-regulated networks and promote cancer cell proliferation proliferation." (PMID 40032852, 2025). "In prostate cancer cell lines, stable ectopic expression of TBL1XR1 was shown to inhibit tumor progression via enhancing AR genes, which exhibit anti-proliferative capabilities." (PMID 40074836, 2025). "In prostate cancer cell lines including LNCaP, C4-2, and TRAMP-C1, honokiol significantly decreased AR levels in a dose-dependent manner, with significant effects observed after 48 h of treatment." (PMID 41020902, 2025). "For example, LNCaP cells, derived from a supraclavicular lymph node metastasis site, express both androgen receptor (AR) and prostate-specific antigen (PSA), making them a valuable model for studying ADT-sensitive prostate cancer." (PMID 40709190, 2025). "More importantly, the AR inhibitor enzalutamide can reduce NSUN2 expression and decrease the level of m5C modification in prostate cancer cells." (PMID 41413017, 2025). "Taken together, these results suggest that in primary prostate cancer, SLC22A3 is upregulated in AR FL-expressing cells but diminished in ARV-expressing cells in a background of C allele SNP rs9364554." (PMID 39858458, 2025). "In prostate cancer, ADT and interference with AR signaling, the cornerstone treatments for advanced disease, profoundly alter redox homeostasis." (PMID 41281744, 2025). "In summary, AR modulates YAP expression through TMPRSS2-ERG, which has significant implications for the progression of prostate cancer." (PMID 39963114, 2025). "TRIM68 interacts with coactivators of AR such as TIP60 and p300 to mediate AR transcription in prostate cancer." (PMID 40723250, 2025). "The results from this study emphasize the importance of incorporating NETO2, HPN, AR, and KLK3 as part of a comprehensive model for prostate cancer prognosis, pointing towards their potential to improve clinical outcomes." (PMID 40034593, 2025). "Molecular docking analysis revealed significant interactions between the androgen receptor (PDB ID: 1r4i), a key target in prostate cancer, and three ligands: Atractylenolide II, Atractylenolide III, and Enzalutamide (ENZ)." (PMID 39980567, 2025).
prostate carcinoma (continued). "In high-grade prostate cancer, tumour-infiltrating lymphocytes (TILs) expressed high levels of the androgen receptor and prostate-specific membrane antigen but less PSA antigen when compared to low-grade prostate cancer." (PMID 40427006, 2025). "In prostate cancer, the CCL5–CCR5 axis has been reported to act as an upstream mediator to inhibit androgen–AR signaling." (PMID 40118451, 2025). "In the progression of prostate cancer, evidence suggests that YAP can regulate AR, in addition to AR’s regulation of YAP." (PMID 39963114, 2025). "We show that NKX3.1 is co-expressed and interacts with AR and FOXA1 in AR-positive prostate cancer cells, both sensitive and resistant to the AR antagonist enzalutamide." (PMID 39858088, 2025). "Hsp90 stays in the cytoplasm while the acetylated AR translocates to the nucleus, binding to the Androgen Response Element (ARE) and RNA polymerase II, which initiates the transcription of prostate cancer‐related genes." (PMID 40026288, 2025). "Despite underexpressing AR, the ACRJ-PC28 line exhibited exceptional sensitivity to abiraterone, consistent with clinical observations that Black patients with prostate cancer respond better to this therapy." (PMID 41038711, 2025). "Specifically, AR has been shown to interact with growth factor receptors like EGFR and TrkA, as well as with metalloproteases in prostate cancer, which can influence AR signaling dynamics and enhance tumor progression." (PMID 40008000, 2025). "In prostate cancer, PRMT5 catalyzes H4R3 methylation at the AR promoter to activate AR transcription." (PMID 40919714, 2025). "Genome-wide CRISPRi screens for modulators of androgen receptor (AR) protein levels using live-cell quantitative endogenous AR fluorescence reporters identify PTGES3 as a new regulator of AR stability and function in prostate cancer." (PMID 41193657, 2025). "In prostate cancer, P-TEFb and BRD4 directly interact with the androgen receptor (AR) to mediate expression of important target genes, such as prostate-specific antigen (PSA)." (PMID 39800748, 2025). "In prostate cancer, OC’s SMYD2 inhibition can destabilize AR, potentially enhancing AR antagonists, PARP inhibitors, and taxanes." (PMID 40564985, 2025). "An androgen-induced agonist conformation and nuclear localization are required for AR ADP ribosylation by PARP7, which in prostate cancer cells is primarily a nuclear enzyme." (PMID 40681873, 2025). "TMPRSS2 is one of the target genes of the AR, and when androgens stimulate TMPRSS2-ERG fusion-positive prostate cancer cells, a significant increase in ERG expression can be observed." (PMID 39963114, 2025). "The spotlight in prostate cancer research has shifted to a protein with a seemingly innocuous acronym, Speckle-type POZ protein (SPOP), due to its profound influence on AR pathway regulation." (PMID 40432836, 2025). "In prostate cancer, PRK1 phosphorylates histone H3 at threonine 11 (H3T11) upon AR activation, facilitating AR-dependent transcription by promoting histone demethylation and RNA polymerase II recruitment." (PMID 40356745, 2025). "Androgen receptor pathway inhibitor (ARPI) monotherapy increases gynecomastia and breast pain in prostate cancer patients compared with androgen deprivation therapy (ADT), while ARPI plus ADT does not significantly differ from ADT alone." (PMID 39935942, 2025).
prostate carcinoma (continued). "Research demonstrates that inhibition of the AR pathway by enzalutamide can upregulate the HER2 signaling pathway, thereby enabling prostate cancer cells to sustain growth and survival through this compensatory mechanism." (PMID 41079787, 2025). "The combination of second-generation androgen receptor (AR) antagonists with androgen deprivation therapy (ADT) has shown good efficacy and safety in advanced prostate cancer." (PMID 41179800, 2025). "Studies in breast and prostate cancer cells demonstrated a role for the citrullination enzyme peptidylarginine deiminase 2 (PAD2) in post-translational regulation of estrogen (ESR) and androgen receptor (AR) signaling." (PMID 41226560, 2025). "Castration-resistant prostate cancer showed the downregulation of SOD2, which in turn increases ROS; this increased ROS induced androgen receptor activation and promoted resistance to anti-androgen therapy." (PMID 40563571, 2025). "Previous studies have demonstrated that androgen deprivation suppresses androgen receptor (AR) signaling, resulting in decreased or dysregulated MCL1 expression and increased apoptosis in prostate cancer cells." (PMID 40872527, 2025). "Second, HSP72 is critical for AR and AR-V7 stability, with HSP72 inhibition decreasing the growth of enzalutamide-resistant prostate cancer models." (PMID 39787247, 2025). "Although it was reported that CCNA2 is an AR-Vs specific or target gene in prostate cancer cells, our finding reveals that dihydrotestosterone increases the ARE occupancy by AR-FL in CCNA2 gene and cyclin A2 expression in AR-FL positive cells." (PMID 40391771, 2025). "In prostate cancer, FOXA1’s interaction with the androgen receptor (AR) enhances AR-mediated transcription, potentially driving tumor progression and castration resistance." (PMID 40623983, 2025). "Furthermore, the possible hormonal influence, indicated by androgen receptor expression in some cases, merits deeper investigation, especially given reports of sex-related incidence patterns and similarities with hormone-sensitive tumors such as prostate cancer." (PMID 41562800, 2025). "In vitro, this model supported the concept that a subset of metastatic prostate cancers that have escaped AR dependence can rely on the FGF–FGFR–MAPK axis for survival, and that pathway inhibition suppresses growth of AR-indifferent tumors." (PMID 41514658, 2025). "In prostate cancer, PRMT4 enhances androgen receptor (AR) signaling via histone methylation at AR target genes, contributing to tumor progression." (PMID 41204384, 2025). "We used IE1/2 RNAi to assess the effect of CMV inhibition in seven CMV+ prostate cancer cell lines representing CSPC (LNCaP, LAPC‐4, VCaP), AR‐driven/adenocarcinoma CRPC (LNCaP‐abl, LREX’), and non‐AR‐driven CRPC (DU145, PC3)." (PMID 40493023, 2025). "In prostate cancer, GAS5 functions by inducing apoptosis and repressing androgen receptor (AR) activity, sequestering the androgen/AR complex and inhibiting the AR signaling pathway, which is vital for prostate cancer cell survival and growth." (PMID 40242248, 2025). "We analyzed seven commonly studied prostate cancer cell lines, representing CSPC (LNCaP, LAPC‐4, VCaP), AR‐driven/adenocarcinoma CRPC (LNCaP‐abl, LREX’), and non‐AR‐driven CPRC (DU145, PC3)." (PMID 40493023, 2025). "Having demonstrated that NXP800, but not its inactive control CCT365248, suppressed AR-responsive genes across multiple prostate cancer cell lines, we further investigated the impact of NXP800 on AR biology." (PMID 39787247, 2025).
prostate carcinoma (continued). "Next, we determined the impact of NXP800 on the growth of both AR signaling inhibitor (ARSI)-sensitive (VCaP) and ARSI-resistant (LNCaP95 and 22Rv1) prostate cancer cell lines." (PMID 39787247, 2025). "Similar to breast cancer where they inhibit E2 signaling, HDAC inhibitors or HDAC1/3 knockdown suppresses AR signaling in prostate cancer cells by preventing recruitment of AR coactivators, SRC1 and p300 to AR target genes." (PMID 40479062, 2025). "In prostate cancer, CD44+/α2β1hi/CD133+ cells undergo cell differentiation to an androgen receptor-positive phenotype similar to prostate cancer in situ." (PMID 39919692, 2025). "In prostate cancer, PER1 interacts with the androgen receptor (AR), serving as a negative regulator of AR activity." (PMID 41451215, 2025). "In prostate cancer, MALAT1 expression strongly correlated with androgen receptor (AR) positivity (90%, p < 0.001)." (PMID 40674376, 2025). "Given the well‐established role of oncogenic transcription factors such as AR and ASCL1 in driving prostate cancer, our investigation extended to evaluating the contribution of novel lineage‐related TFs to cell growth and aggressiveness." (PMID 40091506, 2025). "Z. bungeanum extract inhibited androgen receptor (AR) signaling and downregulated nuclear levels of AR by inhibiting AKT and Cyclin D1 levels in prostate cancer cells." (PMID 40093316, 2025). "The PCA1 cluster exhibited higher CRPC-AR module score compared to PCA2 and PCA3 clusters, suggesting its classification as an AR-positive prostate cancer (ARPC) subtype." (PMID 39743630, 2025). "This study aimed to provide an interim evaluation of the combination of androgen receptor signaling inhibitors denosumab, LRT, and metastasis‐directed therapy (MDT) for prostate cancer with multiple bone metastases (poly‐PCa)." (PMID 41031569, 2025). "Glutamine metabolism in prostate cancer is also regulated by oncogenes like MYC, androgen receptors (AR), and mTOR, with metabolic tracing studies highlighting glutamine’s role in energy and precursor synthesis." (PMID 41179661, 2025). "ETV1 and ERG fusions are present throughout the progression of prostate cancer, while MET, whose expression is repressed by the androgen receptor, appears mainly in advanced PCa and bone metastasis." (PMID 39374163, 2025). "Androgens and androgen receptors (AR) play key roles in prostate cancer development, and TET2 physically interacts with AR and its coactivators to affect AR signaling." (PMID 40599235, 2025). "In this review, we aim to summarize the interactions between AR and YAP in prostate cancer, while exploring their potential impacts on the disease’s development and treatment." (PMID 39963114, 2025). "In the context of prostate cancer, TWIST1 has been shown to induce the overexpression of the androgen receptor (AR), a critical factor in AGA, thereby potentially increasing the sensitivity of HFs to androgens." (PMID 40565255, 2025). "To investigate the regulatory role of HIC1 on AR, we initially assessed the expression of HIC1 and AR in human and murine prostate cancer cell lines (including VCaP, PC3, DU145, LNCaP, and RM‐1 cells)." (PMID 41050263, 2025). "For example, CDK7 is an important regulator of both factors, at least in part because it phosphorylates MED1 to enhance AR- and MYC-regulated transcription in prostate cancer." (PMID 40163908, 2025). "The focal adhesion scaffold protein, PXN shuttles between focal adhesion sites and the nuclear matrix, interacts with AR and glucocorticoid receptor (GR) through the C-terminal LIM domain and functions as coactivator of both the receptors in prostate cancer." (PMID 40181329, 2025). "EZH2 targeted proteolysis targeting chimera (PROTAC) is a potential attractive therapeutic approach for treating invasive prostate cancer that relies on EZH2 and AR connected circuits." (PMID 41200193, 2025).
prostate carcinoma (continued). "As a result, AR, TREM2, and APOE are overexpressed in prostate cancer and correlate with poor prognosis The role of SPP1-expressing TAMs in tumor progression is under active investigation, and high SPP1 expression is linked to an unfavorable prognosis." (PMID 41417432, 2025). "In prostate cancer (PCa), upregulation of the TREM-1 mediated the activation of androgen receptor signaling in macrophages to promote PCa-derived cancer cell progression." (PMID 39744496, 2025). "In prostate cancer, OC inhibits dihydrotestosterone (DHT)-induced ERα/AR cross-talk, reducing PSA expression by 80% in LNCaP cells via the dual blockade of ERK1/2 and AKT phosphorylation." (PMID 40564985, 2025). "Our analysis revealed that several maize miRNAs potentially target key regulators of prostate-cancer signaling, including PTEN, IGF1R, AR, FOXO1, GSK3B, and BCL2." (PMID 41440174, 2025). "We functionally validated the direct interaction between AR and the TXNIP promoter by ChIP in prostate cancer cells." (PMID 41213907, 2025). "•The AR represses FAM111A protease transcription in multiple castration sensitive and resistant prostate cancer cells." (PMID 40446667, 2025). "Molecular docking analyses demonstrated that Capillarisin has a high affinity for the androgen receptor (AR), and molecular dynamics simulation was performed to further verify the binding stability, indicating that Capillarisin may exert its pharmacological effects in prostate cancer." (PMID 40331986, 2025). "NED is a mechanism with which prostate cancer cells evade the inhibitory effects of API therapy, turning to AR-independent drivers of proliferation." (PMID 39941808, 2025). "In prostate cancer, apolipoprotein E (APOE) in the TME binds to TREM2 on macrophages and promotes androgen receptor (AR) expression, which further upregulates the transcription of immune mediators such as IL-10, TGF-β1, IL-23A, and CCL2." (PMID 41417432, 2025). "AR amplification is found in approximately 20-80% of CRPC cases, compared to its rarity in treatment-naive prostate cancer." (PMID 41235005, 2025). "Beyond androgen receptor–targeting peptides, MSS1—an optimized AKAP4-mimetic peptide developed to modulate sperm motility—also decreased prostate cancer cell viability." (PMID 41092058, 2025). "In addition to its classic AR pathway inhibition, enzalutamide has also been found to exert a mechanism of prostate cancer inhibition through non-AR inhibition or combine treatment, which further strengthens its position as a cornerstone of prostate cancer treatment." (PMID 39097593, 2024). "In prostate cancer, key roles have been attributed to CYP17A1 and the sustained intra-tumoral synthesis of 5α-dihydrotestosterone, which is a more potent AR agonist than testosterone." (PMID 39682707, 2024). "Altogether, we characterize NSD2 as an essential AR neo-enhanceosome subunit that enables its oncogenic activity, and position NSD1/2 as viable co-targets in advanced prostate cancer." (PMID 39251788, 2024). "In line with our results, miR-1 was found to be related to androgen receptor activity and the PI3K signalling pathway in prostate cancer." (PMID 38956544, 2024). "In prostate cancer, FOXA1 is known to have AR-dependent and AR-independent activities; moreover, in those that are AR-dependent, FOXA1 can exert both positive and negative effects on expression of AR-regulated genes." (PMID 38528115, 2024). "Preclinical investigations have demonstrated the ability of AR-RIPTAC to successfully target and kill prostate cancer cells." (PMID 38201308, 2024). "In a patient-derived model of treatment-resistant lethal prostate cancer, CCS1477 inhibited tumor growth and androgen receptor signaling." (PMID 39407454, 2024). "In a study on prostate cancer, miR-1207-3p regulated the androgen receptor via FNDC1/fibronectin, demonstrating the promoting effect of FNDC1 on androgen receptor expression." (PMID 38649819, 2024).